IL10 (interleukin 10)
Diseases named in the same sentence as IL10 in open-access papers (continued):
Sharing a sentence is not in itself a finding about the gene and the disease.
infection (continued). "It is possible that the secretion of IL-1β, IL-6, IL-10, and TNFα in the choriodecidua region after infection with Escherichia coli would favor their trans-membranal translocation to the amnion and thereby exert their effect on the whole membrane." (PMID 18078521, 2007). "We infected cohorts of mice with either LCMVARM or LCMVClone13, collected their sera at various time points post-infection (p.i.)and measured the IL-10 levels by ELISA." (PMID 17570849, 2007). "IL-10 is an important endogenous suppressor of infection-stimulated bone resorption in vivo, and it appears that the anti-osteoclastic mechanisms induced by IL-10 on bone are more effective than those mediated by IL-4." (PMID 17239241, 2007). "IL-10 is known to reduce the inflammatory response in this infection, mainly characterized by the production of IFN-γ." (PMID 17555592, 2007). "Predicted ranges for IFN-γ and IL-10 all correlate with studies measuring cytokine levels at the infection site." (PMID 17953477, 2007). "On the other hand, we proposed that the prominent production of IL-10 from the early stages of the experimental HPAI infection was the compensatory response to overproduction of proinflammatory cytokines such as TNF-α, IL-6 and IL-12." (PMID 17662125, 2007). "In three separate experiments, IL-10 expression was consistently elevated in the dermis and draining LNs of sensitized mice as compared to naïve mice at 36 h post-infection (p = 0.04)." (PMID 18000543, 2007). "Concomitantly, the levels of anti-inflammatory IL-10 increased steadily up to at least 24 h of infection." (PMID 17637846, 2007). "High IL-10 producers were likely to be egg positive with IL-10 production increasing with increasing infection intensity." (PMID 18045464, 2007). "It is clear from our data that IL-10 plays a critical role in inducing T cell anergy during persistent LCMVClone13 infections, and that its effect is most potent early in the immune response." (PMID 17570849, 2007). "We injected LCMVClone13-infected mice with anti-IL-10 antibodies or normal rat IgG on days 0, 2, and 4 after infection." (PMID 17570849, 2007). "Blocking IL-10 early in the infection during T cell priming (days 0–4) led to enhanced LCMV-specific T cell responses and lower viral titers." (PMID 17570849, 2007). "Blockade of IL-10 using neutralizing monoclonal antibody injections in LCMVClone13-infected mice led to dramatically enhanced effector T cell responses at 8 days post-infection." (PMID 17570849, 2007). "On the other hand, we verified that all immunized, infected mice displayed significant production of IL-10 compared with infected group on days 30 and 70 post-infection." (PMID 17714584, 2007). "Beyond day 2 post-infection, LCMVClone13-infected mice had significantly higher levels of serum IL-10 compared to acutely infected mice, and the levels increased with time." (PMID 17570849, 2007). "Levels of IL-10 rose to peak with infection intensity in 11–12 year olds, while levels of IL-4 and IL-5 rose more slowly peaking later in 15–16 year olds." (PMID 18045464, 2007). "As intracellular bacteria began replication (2–96 hr PI), MDMs stimulated with bovine (B1018) and human (Hu6) MAP isolates up-regulated IL-10 mRNA and protein levels over the entire infection period and this peaked from 48-hr to 96-hr PI." (PMID 16478544, 2006). "Previous studies indicated that the renal lymph node (the lymphoid tissue draining the infected lymphatics) has the highest levels of IL-10 mRNA during the chronic phase of infection." (PMID 16542426, 2006). "During primary SIVmac infection, up-regulations of tnf-α, ifn-γ and t-bet responses (days 1–16 p.i.)were stronger whereas il-10 response was delayed (4th week p.i.)compared to SIVagm infection." (PMID 16800882, 2006). "Mice with a single infection showed an increased percentage of IL-10-producing cells perhaps indicative of greater stimulation of the innate immune system." (PMID 16719922, 2006).
infection (continued). "The regulation of IL-10 synthesis in response to H37Rv infection and NAC treatment was similar in healthy subjects and HIV patients." (PMID 16504020, 2006). "It is possible that IL-10 acts at the site of infection to down-regulate LT formation, and it is unlikely that granuloma formation in the peritoneal cavity is mediated by IL-10 in infected jirds." (PMID 16542426, 2006). "That is, temperature levels were elevated, IL-12 levels were lower, and IL-10 levels were relatively unchanged during infection." (PMID 16571136, 2006). "In contrast, both burn and infection get a late IL-10 (CARS) response, which is then associated with a return to normal weight in the infection group." (PMID 16168063, 2005). "Phenotypic analysis revealed that CD4+ T cellsexpressed IL-10 during infection across groups, but only ST2–/– infected mice showed higher expression intensity, measured as themean fluorescence intensity (MFI) of TNF-α and IFN-γ,indicating a shift toward a proinflammatory phenotype." (PMID 41365681, 2026). "Notably, infection of the 129S6/SvEv IL10-/- mice with SPtA replicated key features observed in humans." (PMID 42238882, 2026). "However, the infection predominantly induces a Th2‐biased immune profile, characterized by elevated levels of IL‐4, IL‐5, IL‐10, IL‐23, and IL‐13, which appears to support parasite survival within the host." (PMID 41503693, 2026). "IL‐10 production is related to inhibiting anti‐inflammatory cytokines and chemokines in the initial stages of the lesion, essential for the establishment of the infection." (PMID 41500977, 2026). "Once the infection is controlled, anti-inflammatory cytokines such as interleukin-10 (IL-10) and transforming growth factor-beta (TGF-β) counterbalance this process, restoring the hypothalamic set point and promoting heat dissipation via sweating and vasodilation." (PMID 41597079, 2026). "Infection induces lower secretion of IL‐6, IL‐10 and IL‐12 during maturation." (PMID 41500977, 2026). "In non‐lethal infections, IL‐10 balances pro‐inflammatory responses, promoting host survival." (PMID 41461395, 2026). "Furthermore, STAT1 deficiency markedly reduced proportions of IFN-γ-producing CD8+ T cells and interleukin-10-producing CD4+ T cells at day 7 post-infection." (PMID 41910261, 2026). "Cytokines such as IL-8, and IL-10 were markedly elevated during infection episodes." (PMID 41988203, 2026). "Furthermore, the expression of TLR4, IL-1β, IL-6, and IL-10 was up-regulated at 24 h post infection in the common carp (Cyprinus carpio) spleen in response to A. hydrophila." (PMID 40298788, 2025). "Next we analysed whether administering anti-IL-10 could enhance the immune response to Salmonella and improve infection control in iron-overloaded Tim3−/− mice." (PMID 40939292, 2025). "At day 8 post-infection anti-IL-10 was injected in Tim3−/− mice once." (PMID 40939292, 2025). "Also, LRRK2 influences the release of the anti-inflammatory cytokine IL-10 in mouse macrophages following infection with Mycobacterium tuberculosis." (PMID 40867920, 2025). "On the other hand, during local infection, IL-10 facilitates the survival of the bacteria." (PMID 41425551, 2025). "Notably, at 35 days post-infection, L. (V.)guyanensis elicited higher IL-10 production in the skin than did the hybrid parasite." (PMID 41017914, 2025). "During infection, LPS-induced KLF4 expression can promote IL-10 release, particularly in the early course of infection, while later it may contribute to the release of high mobility group box 1 protein (HMGB1), a rather pro-inflammatory mediator." (PMID 40313940, 2025). "Our findings suggest that IL-10 may act more as a secondary regulator than a primary indicator of infection." (PMID 40526709, 2025). "Notably, only the anti-inflammatory cytokine IL-10 was elevated, suggesting potential immune modulation during infection." (PMID 41150405, 2025).
infection (continued). "Importantly, injection of anti-IL-13, at 2- and 4-days post CR infection, diminished local secretion of IL-10 and IL-22." (PMID 40591723, 2025). "Conversely, the anti-inflammatory factor IL-10 was notably reduced due to the infection (P < 0.05)." (PMID 40329327, 2025). "Although CD8 T cell deficiency has a minimal, if any, effect on the establishment of splenic MHV68 latent reservoir at 16 days post-infection, increased numbers of MHV68-specific CD8+ T cells observed in IL-10-/- mice are associated with attenuated MHV68 latent reservoir." (PMID 40444948, 2025). "We investigated the effects of mPGES-1 inhibitors (MF63 and MK886) on the production of pro-inflammatory cytokines (TNF-α, IL-1β, and IL-6), the anti-inflammatory cytokine IL-10, and the chemokine IL-8 in macrophages infected with E. coli at a multiplicity of infection (MOI) of 5:1." (PMID 40666730, 2025). "Furthermore, we found distinct cytokine profiles among groups, especially the marked increase of TNF-α and IL-10 in infection-induced ALI and IL-1β in gastric aspiration." (PMID 39969856, 2025). "Alternatively, the timing of sample collection relative to infection may have influenced our ability to detect regulatory effects, as IL-10 dynamics can vary considerably during the course of infection." (PMID 40526709, 2025). "These IL-10-producing effector CD8+T cells disappear in later stages as the infection is controlled, but IL-10 producing CD4+T cells (in SLOs) persist, indicating the involvement of different mechanisms for IL-10 production by these two different cell types (CD8+ and CD4+T cells)." (PMID 41009359, 2025). "Butyrate also has the potential to restore IL-10 levels in the lungs by inhibiting histone deacetylases in myeloid-derived suppressor cells, which in turn reduces persistent pulmonary inflammation during infection." (PMID 40062854, 2025). "Before infection, aging was associated with increased expression of inflammation-related markers (Il10, Tnfa, and Il1b) in VAT, but not in SCAT." (PMID 41145556, 2025). "Instead, it seems that IL-10 mediates the suppression of CD4+ T cell function, leading to impaired virus-specific antibody production within the lungs and an increased susceptibility to infection." (PMID 40431705, 2025). "On the other hand, in visceral leishmaniaisis, IL-10 upregulation may be critical for protective immune suppression, predominantly during the initial stages of the infection, highlighting the importance of timing in the therapeutic modulation of this cytokine." (PMID 40572185, 2025). "However, many pathogens induce IL-10 upregulation during infection and exploit its immunosuppressive activity to evade the host immune system, potentially promoting a microenvironment conducive to their persistence and survival." (PMID 41426569, 2025). "The results showed that the expression levels of apoptotic (bax, cas3, and cas9), inflammatory (tnfa, il8, and il10), and antibacterial (hep1) genes peaked on day 2, and the expression of hep2 significantly increased on day 4 and continued until day 14 post-infection." (PMID 40563315, 2025). "As expected, IL-10 levels showed a decreasing trend over time in response to the infection." (PMID 40149081, 2025). "In the context of infection, murine B cell-derived IL10 is shown to be effective in immune counter-regulation during cytomegalovirus infection by restricting excessive plasma cell expansion and the amplitude of virus-specific CD8+ T cells in response to the disease." (PMID 41191641, 2025). "Other aspects of the IL-10–KO mouse are consistent with exogenous infection." (PMID 39817448, 2025). "During infection, neutrophils produce IL-10, an immunosuppressive cytokine that may reduce iNOS expression, affecting infection responses." (PMID 40704794, 2025). "Univariate analysis showed IL-10 to be higher in the infected group, potentially marking susceptibility to infection, although the difference was not significant by Mann–Whitney U test." (PMID 41354730, 2025).
infection (continued). "The decreased level of IL-10 in the abortion group was in line with earlier research, which showed that B. abortus, a persistent intracellular pathogen, inhibits macrophage immune activation to release IL-10 early during infection." (PMID 40872670, 2025). "Additionally, IL-10 secretion by splenocytes from all infection time points was significantly inhibited after ConA stimulation compared to controls." (PMID 40918106, 2025). "Akkermansia can protect animals from infection by pathogens, block the virulence factor expression of Fusobacterium nucleatum, increase anti-inflammatory responses mediated by IL-10 and expression of tight junction proteins that limit pathogen translocation across epithelial barriers." (PMID 41472112, 2025). "We observed robust IL-10 expression in infected μMT-/- mice at 99 days post-infection." (PMID 40972121, 2025). "From our LTT analysis, we found that fluoxetine-pretreated Il10−/− infected mice were less lipid tolerant compared to fluoxetine-pretreated infected wild-type mice, demonstrating that IL-10 is necessary for fluoxetine-mediated increased peripheral uptake of lipids during infection." (PMID 39951524, 2025). "Furthermore, application of deferoxamine in C. jejuni-infected hma IL-10−/− mice at 2 days post infection, diminished recruitment of colonic neutrophils and T lymphocytes and inhibited ex-vivo IFN-γ secretion in the colon, the kidneys and in the serum." (PMID 40395728, 2025). "In particular, no expression of IL-10 was seen upon VR-2332 infection, whereas dramatic transcriptional upregulation of IL-10 was evidenced in GNU-2353- and GNU-2377-infected PAM-KNU cells throughout the infection period, and IL-10 expression was more robust in GNU-2353-infected cells at 48 hpi." (PMID 40302751, 2025). "Furthermore, HIV-1ADA infection of PBMCs also resulted in a more significant down-regulation of anti-inflammatory cytokines IL-4 and IL-10, compared to HIV-1IndieC1-infection or control uninfected sample." (PMID 40313367, 2025). "After a 24-hour incubation period, as the infection progressed, IL-10 was also detected." (PMID 40896724, 2025). "In addition, we observed significant changes in the levels of IFN-γ, IL-4, and IL-17A during the early stages of infection, while the inhibitory cytokine IL-10 exhibited a significant increase in the later stages." (PMID 40742129, 2025). "Therefore, the IL-10-modulating activity of these Streptomyces extracts should be further investigated in vivo to clarify their overall effect on infection outcomes." (PMID 40872549, 2025). "SarA signaling through STAT3 drives M2 macrophage polarization during systemic Salmonella Typhimurium infection, while IL-10 secreted by T and B cells is required for dissemination of Salmonella Typhimurium from the gut to systemic sites of infection in a mouse model." (PMID 40188438, 2025). "Current evidence suggests that IL-10 plays conflicting roles during infection." (PMID 40953078, 2025). "This suggests that the simultaneousrise of pro-inflammatory cytokines and IL-10 may help protect tissuein Y strain infections." (PMID 40488037, 2025). "Moreover, certain subsets of plasma cells produce anti-inflammatory cytokines such as interleukin-10 (IL-10) and IL-35, contributing to immune regulation throughout infection." (PMID 41246314, 2025). "The ROC curves were used to evaluate the predictive value of SP-D and IL-10 for severe infection." (PMID 40160824, 2025). "Fully differentiated effector CD8+T cells in their target organs also secrete a large amount of an anti-inflammatory cytokine called IL-10 at the site of infection or inflammation at the peak of their antiviral immune response to prevent exaggerated inflammation or tissue damage." (PMID 41009359, 2025). "Notably, the infection-induced expression of Il10, Tnfa, and Il1b was significantly higher in aged mice compared to young mice." (PMID 41145556, 2025).
infection (continued). "Studies show that the production of cytokines is essential and modulated by the type of cellular response represented at the beginning of the infection by the increase in inflammatory cytokines and transition to anti-inflammatory cytokines with IL-10, for example." (PMID 40005520, 2025). "Structural equation modeling (SEM) has been utilized to show that the balance between inflammatory IL-17 and regulatory IL-10 could determine the outcome and time course of C. jejuni M1 infections." (PMID 39964091, 2025). "Infection of the strain B10.O20 resulted in 15-350× increase of splenocytes’ production of IFNγ IL-2, IL-4, IL-6, IL-10 and IL-17." (PMID 41164189, 2025). "However, in mice infected with Δplp1 parasites, IL-10 increased only during the high dose infection and was concomitant with the IFN-γ response, consistent with homeostatic regulation of a localized proinflammatory state." (PMID 40166190, 2025). "The absence of TLR2 and TLR4 results in impaired phagocytosis and reduced levels of TNF-α, IL-6, IL-10, and nitric oxide, which could promote a persistent infection." (PMID 41346968, 2025). "Viral latency transcripts were highly enriched in Bla+ data sets of both M2.Stop and WT MHV68, however, only AID+Bla+ samples from WT MHV68 infection showed increased transcription of Il10 and Irf4, which is consistent with previous work demonstrating that M2 upregulates their expression." (PMID 39843898, 2025). "Importantly, during the later phase (7 days post-infection), there was a significant upregulation of M2-/Th2-related markers, including Arg-1, IL-4, and IL-10, in K. pneumoniae_OMVs-immunized mice relative to the PBS group." (PMID 41472051, 2025). "Interestingly, the anti-inflammatory cytokine IL-10 also showed increased levels post-infection (p < 0.0008)." (PMID 40895521, 2025). "Cross-referencing with the KEGG and Reactome databases revealed that the infection-related pathways (IL-17, IL-10, and TNFα signaling) were significantly enriched among the downregulated genes, indicating the reduced activity of these pathways in the classical and intermediate monocytes of patients." (PMID 41280901, 2025). "Transforming growth factor β (TGF-β), interleukin (IL)-10, and IL-4 were neutralized upon infection with mouse-adapted SARS-CoV-2 (CMA3p20), a model of mild disease; lung inflammation was quantified by histology and flow cytometry at early and late time points." (PMID 40854598, 2025). "The decrease in IL-10 levels observed in these patients is consistent with the concept of immune exhaustion, where the immune system’s regulatory capacity is overwhelmed by the persistent inflammatory stimuli from ongoing infections." (PMID 39885417, 2025). "The infection stimulates T helper 2 lymphocytes, which produce interleukins (IL)-4 and IL-10." (PMID 40421174, 2025). "IL-10 exhibits distinct biological functions depending on the stage of infection, whether acute or chronic." (PMID 41156600, 2025). "As all three mouse IL-20RA cytokines are constitutively expressed and IL-10 is induced after infection, this suggests that both IL-19 and IL-20 could be the upstream effectors to induce IL-10." (PMID 41550952, 2025). "Based on our findings, it can be inferred that IL-10 may be protective against a severe course of infection or the manifestation of symptoms." (PMID 40732660, 2025). "Interestingly there was a small, but significant, increase in plasma levels of IL-10 3 hr post-infection." (PMID 39992703, 2025). "Contrary to what occurs in animals whose predominant profile is Th2, characterised by higher amounts of IL‐4, IL‐5, IL‐10 and TGF‐β and cells with a lower capacity to destroy the protozoan and, therefore, responsible for a greater susceptibility to infection and the appearance of clinical signs." (PMID 40033570, 2025).